TNF (tumor necrosis factor)
Diseases named in the same sentence as TNF in open-access papers (continued):
Sharing a sentence is not in itself a finding about the gene and the disease.
Sepsis (continued). "In this regard, higher levels of NETs’ production correlated with the worsening and severity of sepsis and organ failure in humans; moreover, NETs’ formation during the initial stages of sepsis was also positively correlated with levels of key inflammatory cytokines IL-8, IFN-gamma, and TNFα." (PMID 35052592, 2021). "On the day after the clinical diagnosis of sepsis, ex vivo LPS-induced TNF-alpha secretion was found to be significantly lower in nonsurvivors as compared with survivors of sepsis." (PMID 34945111, 2021). "During sepsis, LPS/LTA can activate the MAPK signaling pathway, and further accelerate the production of proinflammatory cytokines, such as IL-1β, IL-6, and TNF-α, which form the cytokine cascade, and eventually leads to cell apoptosis and multiple organ dysfunction." (PMID 34483941, 2021). "When sepsis cases were separated into subgroups by genotype, carriers of the GG/GC genotypes at the NLRP3 29940G>C site exhibited significantly higher NLRP3 mRNA and TNF-α levels than carriers with the CC genotype." (PMID 34172780, 2021). "The possible role that the TNF-alpha inhibitor played in the development of SCC on HS lesions, and concomitant sepsis, was unclear, because there was just a significant baseline immune dysregulation in their patient and an increased infectious risk were clearly reported with this drug class." (PMID 34829823, 2021). "The most important mediators of sepsis that have been studied in the pathogenesis of AP and SAP are tumor necrosis factor alpha (TNF-α), interleukin (IL)-1β, IL-6, platelet activating factor (PAF), IL-10, C5a, reactive oxygen species and reactive nitrogen species." (PMID 33912302, 2021). "One study has reported that the expression of TNF-α was downregulated in Irak1-deficient macrophages when TLR2 or TLR4 were activated, thereby weakening the response to the lethal effects of sepsis caused by LPS or Gram-negative bacteria." (PMID 34421892, 2021). "None of the dogs in this study suffered from sepsis; therefore, we can assume that the levels of TNF-α and IL-6 do not increase in pancreatitis without septic conditions." (PMID 33803665, 2021). "Collectively, microglia can be activated by LPS or cytokines such as TNF-α and IL-6, and destroy the BBB during the initial phase of sepsis by directly mediating neuroinflammation in the brain and participating in the direct spread of neuroinflammation in the course of SAE." (PMID 34804998, 2021). "In line with the previous studies, we confirmed that GIT1 deficiency partially reversed miR-122-5p inhibition-mediated protective effect on sepsis as evidenced by increased cell apoptosis, triggered ROS production, elevated LDH content, enhanced TNF-α level, and reduced SOD activity." (PMID 34002676, 2021). "Cit-AuNP treatment performed 2 h after induction of sepsis reduced cerebral TNFα concentration, but not other cytokines, compared to mice with sepsis treated with saline." (PMID 33608025, 2021). "According to some literatures on NAFLD, some immune-related loci associated with NAFLD could exhibit some level of pleiotropy influencing sepsis with genes of CD14, IL-6, MIF, TLR4, and TNF." (PMID 34938184, 2021). "In the current study, a highly significant difference was observed between S-AKI and non-AKI groups for the genotype distribution of TNF-α (rs1800750) among whole patients, sepsis, and acute septic shock groups." (PMID 34692772, 2021). "This assumption is supported by the cooperation between TNFα-induced NF-κB and the JAK/STAT3 pathway which has recently been demonstrated in brain pericytes, and by the inhibitory effects of TCZ on NF-κB in a rat model of sepsis." (PMID 34975837, 2021). "According to previous studies, increased levels of circulating cytokines like TNF‐α, IL‐1β and IFN‐γ are typical characteristics of sepsis, which may induce endothelium dysfunction, pathological procoagulant state and exacerbate liver injury as well." (PMID 33982381, 2021).
Sepsis (continued). "Unfortunately, despite observations of improved mortality in murine sepsis models following blockade of TNF-α or IL-1 signaling, several clinical trials of TNF or IL-1 inhibitors failed to achieve the endpoint for patients with sepsis." (PMID 34253862, 2021). "In the sepsis group, significant correlations were found between IL-8 and MIP-1α (ρ = 0.549, p < 0.0001), TNF-α and MIP-1α (ρ = 0.374, p < 0.0001), MIP-1α and IFN-γ (ρ = 0.367, p < 0.0001), and TNF-α and IFN-γ (ρ = 0.234, p = 0.0021)." (PMID 34654467, 2021). "Using CLP, a clinically relevant murine model of gram-negative polymicrobial sepsis, we observed that FeTPPS treatment markedly inhibited caspase-11-dependent release of IL-1α and IL-1β, but did not affect the secretion of TNF or IL-6." (PMID 33854044, 2021). "Furthermore, the animals given neutralizing antibodies against TNF-α and IFN-γ are protected from death following SARS-CoV-2 infection, sepsis, HLH, and cytokine shock." (PMID 34946543, 2021). "Growing evidence suggests that besides causing severe flu-like symptoms in humans, SARS-CoV-2-driven increased morbidity is also associated with a ‘cytokine storm’ comprising surplus release of tumor necrosis factor-α (TNF-α) and IFN-ɣ, triggering multiorgan failure and sepsis." (PMID 34544548, 2021). "In our study, IL‐6 and TNF‐α expression displayed the same profile: 2 h after sepsis induction, a sharp increase was detected, with nevertheless one exception: for TNF‐α, in non‐supplemented rats where this increase was not significant (p = 0.058)." (PMID 34288548, 2021). "The prediction of CFIG targets showed that the CFIG of XBJI could affect sepsis synergistically through genes such as TAK1, TNF-α, IL-1β, and MEK1 in the pathways of MAPK, NF-κB, PI3K-AKT, Toll-like receptor, and tumor necrosis factor signaling." (PMID 34938184, 2021). "For example, TNF-α, a member of TNF, was usually detected in the blood of patients with sepsis and was reported to induce NO production significantly and increase the death rate in LPS-induced sepsis mice." (PMID 34938184, 2021). "For example, netrin-1 protected against acute lung injury sepsis in rats through decreasing the expression of IL-1, IL-6, and TNF-α, and in a porcine model of acute lung injury, through ameliorating TNF-α, IL-1β, IL-6 and IL-8." (PMID 35250531, 2021). "As sepsis-induced disruption of tissue homeostasis leads to aberrant regulation of both anti- and pro-inflammatory cytokines (CKs), we sought to determine the expression of IL-1β, IL-6, IL-10, TGF-β1, and TNFα, the main drivers of tissue inflammation." (PMID 33803290, 2021). "Furthermore, animals given neutralizing antibodies against TNF-α and IFN-γ are protected from death following SARS-CoV-2 infection, sepsis, hemophagocytic lymphohistiocytosis (HLH), and cytokine shock." (PMID 34946543, 2021). "The first excision time from burn was not a significant predictor (P = 0.716), while burn index (P = 0.0003), ABSI (P = 0.013), TBSA percentage (P < 0.0001), third-degree TBSA percentage (P = 0.0003), TNF-α (P = 0.0007), and PCT (P = 0.016) were all predictors for sepsis in severe burns." (PMID 33833617, 2021). "In the process of sepsis, NK cells may be excessively activated and produce excessive amounts of IFN-γ and TNF-α, thus leading to systemic inflammation aggravation, MODS, and an increased risk of mortality." (PMID 34335278, 2021). "Here we demonstrated a great increase in TNFα mRNA expression and a slight and not significant increase in TNFα protein concentration in brain of mice 6 h after induction of sepsis, and 20 nm cit-AuNP treatment reduced both TNFα protein and mRNA levels." (PMID 33608025, 2021). "Compared with the burn patients without signs of sepsis, higher levels of TNF-α were observed in burn patients with sepsis." (PMID 33654698, 2021).
Sepsis (continued). "Our results indicate that simvastatin treatment has an important negative immunomodulatory effect in sepsis since it was able to lower the levels of IL-6, TNF-α, IL-1β, and MIF in the peritoneal cavity in our model." (PMID 33110395, 2020). "Addition of PTX to GENT after 1.5 and 4 h of sepsis duration, on the other hand, reduced the TNF-to-IL-10 ratio in lung tissue and effectively prevented this pro-inflammatory response observed with GENT treatment alone at the later stages of sepsis in our model." (PMID 33072121, 2020). "It has been demonstrated that TNF‐induced lethal SIRS in mice, which is used as a model system for sepsis but also for inflammatory bowel disease, is strongly mediated by cell death in the IECs and is associated by efflux of gut microbes into the spleen and MLNs." (PMID 32914580, 2020). "In hearts from adiponectin-knockout mice, there is an increased expression of endoplasmic reticulum stress and inflammatory genes such as TNFα and MCP-1, an effect that is reverted by adiponectin treatment of H9C2 cardiomyocytes with induced endoplasmic reticulum stress and in HUVECs in sepsis." (PMID 33081064, 2020). "Narciclasine significantly suppressed the expression of TNF-α in the lungs when compared to the sepsis group without treatment." (PMID 32076015, 2020). "Besides, our previous research has suggested that ADMSCs secrete a large amount of sTNFR1 to block the activity of TNF-α, thereby reducing the expression of NF-κB, AP-1, and P38 MAPK in sepsis induced ALI." (PMID 32625095, 2020). "TNF-α is considered a key cytokine in the development and course of RA, AIH, as well as sepsis." (PMID 31899535, 2020). "Similarly, in the cecal ligation and puncture (CLP) sepsis model, PAG treatment reduced mRNA and protein levels of pro-inflammatory cytokines IL-1β, IL-6, TNF-α in mice, indicating that H2S potentiates systemic inflammation in sepsis." (PMID 33330130, 2020). "The effects of TNF-suppressing anti-inflammatory agents such as PTX in addition to antibiotics in sepsis should therefore be investigated with different bacterial loads and strains prior to its recommendation as adjunctive sepsis therapeutic." (PMID 33072121, 2020). "A large number of studies have indicated that inflammatory cytokines, such as TNF-α, play a central role in Gram-negative bacteria-induced sepsis and endotoxic shock." (PMID 33123008, 2020). "Tumor necrosis factor-α (TNF-α), a 17 kDa protein and a pleiotropic cytokine, is derived mainly from infectious stimulus-activated immune cells (e.g., macrophages) via a Toll-like receptor (TLR)/nuclear factor-κB (NF-κB) pathway during sepsis." (PMID 33003495, 2020). "Exposure of lipopolysaccharide (LPS)-activated human macrophages to acetylcholine resulted in a dose-dependent inhibition of such proinflammatory cytokines as tumor necrosis factor-α (TNF-α), interleukin 6 (IL-6), and IL-1β, involved in pathological processes of endotoxemia and sepsis." (PMID 32230846, 2020). "TNF-α level was significantly reduced in non-survivors of elderly patients with sepsis on the first day of diagnosis compared to survivors." (PMID 33382782, 2020). "The overproduction of IL-10 was the main predictor of severity and fatal outcome of sepsis, and an increased ratio of IL-10/TNF-α was found in non-survived human patients." (PMID 33333934, 2020). "Even though TNF failed to induce organ injury, it induced sepsis-like symptoms in both mouse strains." (PMID 32410851, 2020). "TNF-α and IL-1 enhance inflammatory cascade by activating macrophages to release certain proinflammatory cytokines such as IL-6 and IL-8, ROS/RNS, and lipid mediators which are essential to sepsis-induced organ failure." (PMID 33158114, 2020). "In PBMC cultures, zoledronate treatment led to an upregulation of HLA‐DR as well as CD40 and CD64 on sepsis monocytes, which at least in the case of HLA‐DR and CD40 could be inhibited by the addition of neutralising reagents against IFN‐γ and TNF‐α." (PMID 31606902, 2020).
Sepsis (continued). "When changes in mRNAs of pro-inflammatory cytokines in lung, liver, and kidney tissues were investigated using real-time PCR, the greatly increased mRNA expression levels of TNF-α, IL-1β, and MCP-1 at 18 h after CLP-induced sepsis were significantly suppressed by stattic administration." (PMID 32943679, 2020). "The elevated concentrations of tumor necrosis factor (TNF)-receptors produced by visceral fat, may lead to a decrease in the harmful effects of excessive TNF production during sepsis." (PMID 32190482, 2020). "Thus, in the AOSD group, FGF-2, GM-CSF, IL-17, IL-18, and VEGF form interrelated networks, whereas in the sepsis group, IFN-γ, TNF-α, IL-8, IL-10, and IL-18 form interrelated networks." (PMID 32381117, 2020). "Studies on both patients with sepsis and sepsis animal model indicated that HMGB1 could facilitate the release of inflammatory cytokines from macrophages, such as: TNF-α, interleukin-6 (IL-6)." (PMID 33552058, 2020). "Analysis using Hdc‐deficient mice showed that the increase in TNFα, IL‐1b, IL‐6 and MCP1 levels in sepsis was attenuated when there was a lack of histamine, indicating that the induced histamine promotes the production of the pro‐inflammatory cytokines." (PMID 32394600, 2020). "Also, circC3P1 dramatically attenuated pulmonary injury, decreased pro‐inflammatory cytokines (TNF‐a, IL‐6 and IL‐1β), cell apoptosis and p‐AKT/AKT levels induced by sepsis." (PMID 32846020, 2020). "Other biomarkers that can indicate the immune state in sepsis patients include apoptosis markers (Bim, Bid and Bac), caspases, leukocyte markers (HLA-DR, PD-1, FOXP3, CD127) and cytokines (IL-2, IL-6, IL-12, IL-17, IL-22, IL-33, TNF-α, IFN-γ, IL-10 and TGF-β)." (PMID 33336293, 2020). "It was demonstrated that CD11c+ DCs harvested from the CLP model are impaired to expressed IL-12p40 and tumor necrosis factor-alpha (TNF-α) upon stimulation with lipopolysaccharide (LPS) or CpG, implying that sepsis has the ability to change DCs’ response to a Toll-like Receptor (TLR) agonist." (PMID 32197507, 2020). "When nonsurvivors of the two groups were compared, the levels of serum IL-1β, IL-2R, IL-6, IL-8, and TNF-α were also lower in SARS-CoV-2 sepsis nonsurvivors." (PMID 33329592, 2020). "A retrospective cohort study of the cytokine response to pneumonia found that levels of IL-6, IL-10, and TNF-α were significantly higher among those who developed severe sepsis (survivors and non-survivors) compared with those who did not." (PMID 32144519, 2020). "IL-6 and TNF-α concurrently stimulate the production of C-reactive protein (CRP) and procalcitonin (PCT), which are the most widely used inflammatory biomarkers in patients with sepsis in clinical practice." (PMID 32778146, 2020). "Liposaccharide (LPS) present in the outer membrane of Gram-negative bacteria is responsible for sepsis as it is a potent tumor necrosis factor-α (TNF-α) stimulator." (PMID 33066447, 2020). "Moreover, the TNF signaling pathway, Toll-like receptor signaling pathway and Jak-STAT signaling pathway were also altered in sepsis patient PBMCs." (PMID 32922168, 2020). "Our findings imply that STAT3 is critical for the production of different pro-inflammatory mediators, including TNF-α, IL-1β, IL-6, and MCP-1, in CLP-induced sepsis, although STAT3 would work coordinately with other transcriptional co-activators or transcription factors." (PMID 32943679, 2020). "In line with our data, TRPV4 inhibition showed no protective effect in TNF-α induced sepsis, whereas it does in LPS induced sepsis." (PMID 32974355, 2020). "Some immunosuppressive agents have been tried in infectious disease, mostly in sepsis, without satisfactory results, including corticosteroids and TNF-α inhibitors, which was efficient in mouse models." (PMID 32616791, 2020).
Sepsis (continued). "Indeed, it has been demonstrated that neutralization of proinflammatory mediators such as TNF-α and IFN-β during the hyperinflammation phase of sepsis and boost suppressed immunity with IFN-β during the immunosuppression phase both showed therapeutic effects." (PMID 33061831, 2020). "Narciclasine treatment showed significant reduction of TNF-α expression compared to the sepsis group without treatment." (PMID 32076015, 2020). "Serum levels of TNF-a, IL-6, and IL- 10 at 6 h and 30 h were significantly elevated in CLP-induced sepsis in comparisons with those in the sham group (p < 0.05), serum levels of TNF-a, IL-6, and IL- 10 of LDK378 group at 54 h were higher than sham group (p < 0.05)." (PMID 30820191, 2019). "In fact, no TNF-α-positive cells were found in sepsis and control patients in the white pulp, whereas 32 cells/m2 were found in leptospirosis samples." (PMID 31114579, 2019). "Previous study also showed that the expressions of TNF-α and IL-6 were increased by activated JAK/STAT pathway in rat lung tissue with sepsis, and that suppressing the JAK/STAT pathway could alleviate organ dysfunction in septic rats." (PMID 31084615, 2019). "We showed that TNF-α levels are increased in leptospirosis in comparison with the sepsis and control groups, in spite of the lack of regulation of other Th1 cytokines." (PMID 31114579, 2019). "TNF inhibition in sepsis patients has no obvious therapeutic effect and a meta-analysis of all trials seems to suggest only a minimal protective effect in the worst cases of septic shock." (PMID 31787972, 2019). "Tumor Necrosis Factor-α (TNF-α), Interleukin-1β (IL-1β), Interleukin-8 (IL-8, CXCL8), and monocyte chemoattractant protein-1 (MCP-1) are notably elevated during the early phases of infection in the case for sepsis, while IL-6 gradually increases over time." (PMID 31547199, 2019). "In this study, the results showed that knockdown of miRNA-106a reduced LPS-induced the levels of inflammatory factor TNF-α, IL-1β and IL-6, suggesting that inhibiting the expression of miRNA-106a might inhibit the occurrence of AKI induced by sepsis." (PMID 31432993, 2019). "It has been reported that BM-MSCs activated by lipopolysaccharide (LPS) or tumor necrosis factor-a (TNF-a) reprogram macrophages to increase the production of interleukin-10 (IL-10) by secreting prostaglandin E2 (PGE2) and attenuate sepsis and improve survival in mouse sepsis models." (PMID 31336889, 2019). "Likewise, gene expression of these cytokines in gastrocnemius muscle showed that pro-inflammatory IL-6 and TNFα were comparable among NSC and sepsis survivors at 2 weeks (p=0.622 and p=0.565, respectively)." (PMID 31793435, 2019). "Given the heterogeneity of sepsis patients, many clinical trials targeting the hyper-inflammatory response in sepsis, including corticosteroids, and anti-cytokine therapies (e.g., anti-IL1 and anti TNF-α) have yielded disappointing results." (PMID 31708927, 2019). "Because sTNFR1, IL8, and Ang2 reflect pathways that are dysregulated in sepsis and for which therapies are being investigated, such as monoclonal antibodies targeting IL8 and TNF, they should be evaluated as predictive enrichment factors for their designated therapies in future trials." (PMID 31818332, 2019). "Gene expression of TNF-α was not affected by sepsis but depended on the dietary PUFA ingested: it was significantly decreased by dietary EPA (−33% and −56% in the Sham and Sept subgroups, p < 0.05 in general)." (PMID 31534623, 2019). "Male descendants of sepsis fathers, but not female descendants, exhibited lower plasma concentrations of IL-6, TNF-alpha, and IL-10 24 h after injection of LPS." (PMID 29988283, 2018). "The levels of IL-6, TNF-α, and HSP70 decreased within the first 12 h of CVVH in AKI patients with sepsis, whereas the levels of DAMPs at the outlet were temporarily increased after blood passage from the inlet through the dialyzer in survivor AKI patients with sepsis." (PMID 30666251, 2018).